TBX3 (T-box transcription factor 3)
Diseases named in the same sentence as TBX3 in open-access papers (continued):
Sharing a sentence is not in itself a finding about the gene and the disease.
breast carcinoma (continued). "This is significant because TBX2, a homologue of TBX3, was shown to be a powerful pro-proliferative factor in melanoma and breast cancer cell lines which express both TBX2 and TBX3 and there has been an indication that TBX2 and TBX3 can repress each other." (PMID 24098938, 2013). "We have previously shown that over-expression of TBX3 represses human p14ARF by recruiting HDAC 1, 2, 3 and 5 in the MCF7 breast cancer cell line." (PMID 22039763, 2011). "Also, higher expression of TBX3 significantly correlates with better DMFS and DFS in basal-like breast cancer patients." (PMID 38081972, 2023). "To confirm whether SIRT6-OE is sufficient to induce TBX3 downregulation, we ectopically overexpressed SIRT6 in the human HER2 + /Delta16HER2 + breast cancer cell line BT474." (PMID 38081972, 2023). "In the context of HER2-amplified breast cancer, either TBX3 loss-of-function or SIRT6 amplification predicts a worse survival than patients with no alterations in SIRT6 and TBX3 (Log-rank P = 0.0007)." (PMID 38081972, 2023). "Independent of CREB5 and FOXA1, TBX3 expression has been shown to be required for viability of breast cancer cells." (PMID 35550030, 2022). "TBX3 is an oncogene reported in solid tumors, including breast cancer, fibrosarcoma, melanoma and lung cancer but not as yet in hematopoietic neoplasms." (PMID 34807923, 2021). "To determine whether TBX3 can promote a tumorigenic phenotype in breast cells, we stably overexpressed or repressed TBX3 in the human mammary epithelial (HMLE) cell line and the MCF7 breast cancer cell line." (PMID 31910858, 2020). "Overexpression of TBX3 at early pre‐invasive stages (CCL, DCIS) of breast cancer progression, inducing other molecular regulators of EMT (including SLUG and TWIST1), acts as an enabler to set the stage for basement membrane breakdown and invasion into adjacent stroma." (PMID 30697731, 2019). "Using the ICGC US donor cohort, we found that TBX3 mRNA levels were elevated in tumor cells of several cancer subtypes, including breast cancer (data not shown)." (PMID 30697731, 2019). "We have here demonstrated a role for both isoforms of TBX3 (isoform 1 and 2) in promoting the transition from non-invasive to invasive breast cancer." (PMID 27553211, 2016). "T-box transcription factors (TBX2 and TBX3), WNT signaling, fibroblast growth factors (FGFs), bone morphogenetic proteins (BMPs), and parathyroid hormone-related protein (PTHrP) are among the molecular players identified in both mammary gland development and breast cancer biology." (PMID 40001874, 2025). "Collectively, these results suggest that TBX3 may be facilitating the process of early invasion even at the earliest stages of progression (i.e. CCLs, DCIS), and offer potential roles for downstream EMT‐related proteins such as SLUG and TWIST1 in the invasiveness of early‐stage breast cancer." (PMID 30697731, 2019). "While in tumor cells driven by different oncogenic events, such as MCF7 breast cancer cells, the expression and function regulation of USP15 on TBX3 has not shown such direct correlation." (PMID 38750011, 2024). "Importantly, TBX2 and TBX3 may additionally play non-redundant roles in breast cancers." (PMID 35846378, 2022). "To examine the tumorigenicity of TBX3 isoforms, we stably overexpressed either TBX3iso1 or TBX3iso2 in non-tumorigenic, ductal carcinoma in situ (DCIS)-like 21NT breast cancer cell lines." (PMID 31570773, 2020). "TBX3 does not appear to promote oncogenesis of RMS cells, unlike what has been observed in melanoma and breast cancer cells." (PMID 30979887, 2019).
melanoma (40 papers, 2006 to 2025). A malignant, usually aggressive tumor composed of atypical, neoplastic melanocytes. "Tbx3 is likely to play a role in adult tissues as well, because Tbx3 has been implicated as an oncogene and was found overexpressed in cell lines from several cancer types, including melanoma and hepatoma." (PMID 25343378, 2014). "We also examined the levels of Tbx2 and Tbx3, which have been associated with E-cadherin downregulation in melanoma cells." (PMID 22911700, 2012). "Similarly, increased expression of TBX3 was seen in melanoma cell lines where TBX3 represses E-cadherin expression and causes increased invasiveness and tumor formation in vivo." (PMID 26579496, 2015). "Likewise, TBX3, a member of the T-box family of transcription factors, functions as a direct repressor of p21 expression and has been implicated in a broad spectrum of cancers, including breast, ovarian, cervical, pancreatic, bladder, liver, and melanoma." (PMID 41154614, 2025). "However, considering that Tbx3 has been implicated in metastasis of cervix, breast, head and neck squamous cell carcinomas, as well as melanomas, it is tempting to speculate that this repression may take place in vivo as well, especially during metastasis." (PMID 23082988, 2012). "With this in mind, we explored the potential of PO, which was previously shown to inhibit TBX2 and TBX3 in TBX2‐/3‐dependant melanoma and rhabdomyosarcoma cells, to inhibit levels of these two proteins in PDAC cells." (PMID 40717225, 2025). "Similar to the regulatory mechanism under BRAFV600E–induced thyroidal transformation, USP15 is also transcriptionally activated by BRAF/MAPK pathway during melanoma genesis and controls TBX3 stability." (PMID 38750011, 2024). "This is an important finding as it shows that these three drugs maintain their ability to downregulate either TBX2, TBX3 or both in TBX2/TBX3‐dependent non‐melanoma cancer cell lines." (PMID 39403898, 2024). "On the one hand, it was reported that TBX3 was overexpressed in most human malignancies such as melanoma, breast, ovarian and bladder cancer." (PMID 38413457, 2024). "The highly homologous T‐box transcription factors TBX2 and TBX3 are critical for embryonic development, and their overexpression in postnatal tissues contributes to a wide range of malignancies, including melanoma and rhabdomyosarcoma." (PMID 39403898, 2024). "Clinically, TBX3 level positively correlates with that of USP15 as well on our melanoma tissue array." (PMID 38750011, 2024). "Tbx3 is targeted by miR-137 in melanoma, inhibiting cell migration, and in embryonic stem cells, reducing cell proliferation." (PMID 34068962, 2021). "We then assessed TBX3iso1 to TBX3iso2 ratios in additional tumor types which overexpress TBX3, including melanoma, colon, and pancreatic cancer." (PMID 31570773, 2020). "TBX3 levels are additionally up-regulated in several cancer types, including breast, melanoma, colorectal, pancreatic, cervical, ovarian, gastric, and prostate cancers, suggesting its potential role as an oncogenic driver in multiple cancer types." (PMID 31570773, 2020). "Rhabdomyosarcomagenesis involves, in part, the prolonged activation of serine/threonine kinases such as AKT, and we have previously shown that AKT1 and AKT3 phosphorylation stabilizes the TBX3 protein in chondrosarcoma/fibrosarcoma and melanoma, respectively." (PMID 32098189, 2020). "In the case of deregulation, TBX3 also acquires the potential to become an oncogene in melanoma cells." (PMID 30979887, 2019). "In MCF-12A breast epithelial cells and B16 mouse melanoma cells, TBX3 has been shown to directly repress TBX2 under the control of TGF-β118." (PMID 30979887, 2019). "Functionally, TBX3 has been shown to repress E‐cadherin expression in melanoma 30, and it is a downstream target of the Wnt–β‐catenin pathway." (PMID 29344954, 2018).
melanoma (continued). "The repressor TBX3 is of special importance since it has been shown to be up-regulated in melanoma, and a key contributor to the formation of melanoma." (PMID 27149382, 2016). "The acquisition of an EMT phenotype in melanoma has been shown to be associated with signaling pathways such as Wnt/β-catenin, FGF, Notch, and TGF-β, and the transcriptional repressors SNAIL, TBX3, TWIST, and ZEB." (PMID 27149382, 2016). "Recent evidence show that the embryonically important TBX3 transcription factor is upregulated in a subset of melanomas and plays a key role in promoting melanoma formation and invasion, in part by repressing the cell adhesion molecule E-cadherin." (PMID 25595898, 2015). "We demonstrate that AKT phosphorylation of TBX3 at serine 720 is responsible for the overexpression and nuclear localization of TBX3 in advanced melanoma cells and that it enhances the ability of TBX3 to repress E-cadherin and promote migration and invasion." (PMID 25595898, 2015). "We show that phosphorylation of TBX3 by AKT at serine 720 enhances its ability to repress E-cadherin to promote melanoma migration." (PMID 25595898, 2015). "Although TBX2 and TBX3 share many properties at the molecular and cell biological level, they can be functionally distinct, at least in melanoma cells." (PMID 26579496, 2015). "The overexpression of TBX3 in a subset of melanomas is required for melanoma cell migration and invasion but very little is known about the mechanism(s) responsible for upregulating TBX3 in this cancer." (PMID 25595898, 2015). "We observed a specific association of SOX9 with TMEM158, TBX3, and FYB, suggesting that TMEM158, TBX3, and FYB are direct targets of SOX9 in melanoma." (PMID 25885555, 2015). "TBX3 is upregulated in a subset of melanomas and it contributes directly to melanoma formation and invasion." (PMID 25595898, 2015). "To identify the molecular mechanism(s) that upregulate TBX3 in melanoma we screened a panel of human melanoma cell lines for TBX3 mRNA and protein levels." (PMID 25595898, 2015). "To identify the factor(s) that upregulates TBX3 expression levels in melanoma we considered the AKT pathway because it is known to play key roles in melanoma proliferation, migration and invasion and thus overlap with the oncogenic roles identified for TBX3." (PMID 25595898, 2015). "Together these observations indicate that two pathways critical for melanoma development converge on TBX3 and highlight the importance of TBX3 in melanomagenesis." (PMID 25595898, 2015). "While very little is known about the molecular mechanisms by which TBX3 is up-regulated in melanomas, a recent study has shown that TBX3 transcription is upregulated by BRAFV600E." (PMID 25595898, 2015). "This is supported by the finding that TBX2 or TBX3 are overexpressed/amplified in melanoma and various types of cancer and that the degree of overexpression correlates with invasiveness, distant metastasis, and poor prognosis." (PMID 26579496, 2015). "The two closely related T-box transcription factors TBX2 and TBX3 are considered oncogenes because they are frequently overexpressed in melanoma and various types of human cancer, such as breast, bladder, liver, and pancreas carcinoma." (PMID 26579496, 2015). "In support of this possibility, a microarray conducted by us identified IGF1 and PTEN as possible targets of TBX3 in vertical growth phase melanoma cells." (PMID 25595898, 2015). "Our results identify a novel signalling and transcriptional network linking AKT3, TBX3 and E-cadherin during melanoma migration and invasion and reveals TBX3 as a potential target for anti-metastatic therapeutics." (PMID 25595898, 2015). "Our study identifies a signalling and transcriptional network linking AKT, TBX3 and E-cadherin during melanoma migration and invasion and reveals TBX3 as a potential target for novel anti-metastatic therapeutics." (PMID 25595898, 2015).
melanoma (continued). "In melanoma, TBX2 (and its paralog TBX3) directly repress E-cad by binding to its promoter, causing enhanced invasiveness." (PMID 25344916, 2014). "TBX3 is overexpressed in a number of cancers including a subset of melanomas but its precise role in the progression of this disease still needs to be clarified." (PMID 24098938, 2013). "We previously reported that VGP and metastatic melanoma cells in which TBX3 was depleted maintained a higher proliferative ability than their control cells." (PMID 24098938, 2013). "Hoek and colleagues demonstrated that TBX3 was upregulated in approximately 55% of cell lines obtained from advanced melanoma lesions." (PMID 24098938, 2013). "To confirm that the mechanism by which TBX3 affects melanoma cell adhesion and migration is through repressing E-cadherin, we investigated the levels of this cell adhesion molecule." (PMID 24098938, 2013). "T-box genes/proteins such as TBX2 and TBX3 are overexpressed in several neoplasms, including melanomas, breast, and pancreatic cancer." (PMID 22829758, 2012). "Further supporting the notion that Tbx3 plays a role in cancer development, recent studies have shown that increased levels of TBX3 enhanced melanoma invasiveness by repressing E-cadherin expression." (PMID 22039763, 2011). "For example, TBX3 promotes melanoma, bladder cancer, and liver cancer but inhibits fibrosarcoma." (PMID 38965548, 2024). "Take melanoma as another model where BRAFV600E-induced BRAF/MAPK activation is also the most dramatic carcinogenic mutation, we found knock-down of USP15 resulted in significant TBX3 reduction." (PMID 38750011, 2024). "This study shows for the first time that niclosamide, piroctone olamine and pyrvinium pamoate can negatively regulate the oncogenic TBX2 and TBX3, and it also broadens the anti‐cancer activity of these drugs to include efficacy against melanoma and rhabdomyosarcoma." (PMID 39403898, 2024). "Interestingly, TBX2 and the closely related TBX3 gene are reactivated and/or overexpressed in several cancers including small cell lung carcinoma melanoma, breast, pancreatic, liver, and bladder cancers." (PMID 33731112, 2021). "Furthermore, TBX3 promotes the migration of melanoma cells through directly repressing the cell adhesion protein, E-cadherin, and angiogenesis in pancreatic ductal adenocarcinomas which correlated with increased expression of VEGF-A and FGF2." (PMID 32098189, 2020). "To investigate the possibility that AKT phosphorylation enhances the ability of TBX3 to promote migration we next compared the impact of WT TBX3 and the TBX3 S720A and TBX3 S720E mutants on the migratory ability of the WM1650 RGP melanoma cells using an in vitro cell motility assay." (PMID 25595898, 2015). "Furthermore, western blotting shows that TBX3 protein levels were reduced when the AKT pathway was inhibited in the melanoma cells that overexpress TBX3." (PMID 25595898, 2015). "Furthermore, we provide a novel mechanism by which TBX3 is upregulated in a subset of advanced melanomas." (PMID 25595898, 2015). "It is therefore tempting to speculate that the p38 MAPK pathway may also play a role in regulating TBX3 protein levels in melanoma." (PMID 25595898, 2015). "TBX3 is also upregulated by SOX9 and TBX3 is known to cause increased invasiveness in melanoma, suggesting TBX3 could be an effector gene that drives the invasive phenotype we see in SOX9 high cells and in patients." (PMID 25885555, 2015). "Together these results suggest that AKT3 was the predominant active isoform in our melanoma cell lines and that it may be responsible for upregulating TBX3 in a subset of these melanoma cell lines." (PMID 25595898, 2015). "Indeed, genes that are repressed by Tbx3 such as E-cadherin in melanoma cells and p21 in promoter assays, are highly expressed in Tbx3-positive mammary epithelial cells." (PMID 25343378, 2014). "Together these results show that TBX3 impacts negatively on melanoma cell proliferation." (PMID 24098938, 2013).
melanoma (continued). "Several lines of evidence suggest that TBX3 may be a key contributor to malignant melanoma, a highly aggressive and intractable disease." (PMID 24098938, 2013). "Moreover, both TBX2 and TBX3 show anti-senescence properties, while a dominant negative form of Tbx2 can induce senescence in a melanoma cell line." (PMID 17173667, 2006). "Notably, TBX3 overexpression has been proven to stimulate melanoma formation and invasion." (PMID 38911382, 2024). "For this, we chose the B16 mouse melanoma cell line because it is readily susceptible to senescence after Tbx2 depletion and does not express Tbx3, a highly related T-box factor expressed in many human melanoma cell lines that can potentially regulate similar genes to Tbx2." (PMID 34819350, 2021). "In addition, TBX3 is reportedly deregulated in several cancers including breast, lung and melanoma." (PMID 34807923, 2021). "Indeed, recently it was demonstrated that there is a synergistic co-operation between BRAFV600E and AKT3 in promoting melanoma development and it is therefore possible that TBX3 may also be regulated by AKT3." (PMID 25595898, 2015). "Interestingly, TBX3 mRNA levels remained unaltered when the AKT pathway was inhibited with either AKTVIII or siAKT3 and pre-treatment of both melanoma cell lines with the proteasome inhibitor MG132 rescued TBX3 protein levels when the AKT pathway was inhibited." (PMID 25595898, 2015). "Interestingly, a comparison of TBX3 protein and mRNA levels in a panel of melanoma cell lines in our study suggested that TBX3 may be upregulated via both transcriptional and posttranslational mechanisms." (PMID 25595898, 2015). "More recent studies however suggest that TBX3 may function in advanced stages of melanoma." (PMID 24098938, 2013). "PO was also shown to inhibit cell viability in several cancer cell lines, including two PDAC cell lines and was recently reported to inhibit TBX3, and its homologue TBX2, and to exert anti‐cancer activity in TBX2‐/3‐dependent melanoma and rhabdomyosarcoma." (PMID 40717225, 2025). "For example, in melanoma and breast cancer, TBX2 functions as a pro-proliferative and anti-senescence factor, and TBX3 promotes migration and invasion." (PMID 39912718, 2025). "Niclosamide, piroctone olamine and pyrvinium pamoate were identified as ‘hit’ drugs that exhibit cytotoxicity in melanoma and RMS through their ability to target TBX2 and TBX3." (PMID 39912718, 2025). "PO was previously identified as a TBX2‐ and TBX3‐targeting drug in TBX2 and TBX3 dependent melanoma and rhabdomyosarcoma cells." (PMID 40717225, 2025). "During melanoma development, the phosphorylation at S720 via AKT3 resulted in increased TBX3 protein stability and nuclear localization, which represses the E-cadherin expression leading to cell migration and invasion." (PMID 38965548, 2024). "This study shows that niclosamide, piroctone olamine and pyrvinium pamoate downregulate TBX2 and TBX3 in 501mel melanoma cells and RD ERMS cells and downregulate TBX2 in RH30 ARMS cells with negligible effects on TBX3 levels." (PMID 39403898, 2024). "Multiple oncogenic pathways have been found to regulate TBX3 expression in occurrence of melanoma, lung, thyroid, breast and other types of cancers, here we define USP15 as a critical stabilizer for TBX3." (PMID 38750011, 2024). "“Hit” drugs were validated for their effect on TBX2/TBX3 levels and cytotoxicity in TBX2/TBX3‐dependent melanoma and rhabdomyosarcoma cells." (PMID 39403898, 2024). "In conclusion, we show that TBX3 is a novel direct substrate of AKT3 that mediates its invasive role, in part, by repressing E-cadherin during melanoma progression." (PMID 25595898, 2015). "Here we show for the first time that TBX3 is a novel direct substrate of AKT3 that mediates its role, in part, in melanoma progression." (PMID 25595898, 2015).